METTL3 (methyltransferase 3, N6-adenosine-methyltransferase complex catalytic subunit)
Diseases named in the same sentence as METTL3 in open-access papers (continued):
Sharing a sentence is not in itself a finding about the gene and the disease.
Fanconi anemia (1 paper, 2022). Fanconi anemia (FA) is a hereditary DNA repair disorder characterized by progressive pancytopenia with bone marrow failure, variable congenital malformations and predisposition to develop hematological or solid tumors. "Interestingly, pathway analysis revealed that the identified DSGs in 22Rv1 with METTL3 inhibition were significantly enriched in pathways such as Fanconi anemia pathway, metabolic pathways, base excision repair, aminoacyl-tRNA biosynthesis, and RNA degradation." (PMID 36291932, 2022).
gastritis (1 paper, 2025). Inflammation of the stomach. "Next, we investigated the effect of METTL3 knockout on the phenotype of HPI-induced gastritis in mice." (PMID 40825934, 2025). "Suppression of METTL3 resulted in decreased inflammation and apoptosis, suggesting its potential as a therapeutic target in gastritis management." (PMID 40825934, 2025). "Finally, we established a mouse gastritis model using HP bacterial solution gavage to investigate the regulatory role of the METTL3/CXCL1/NF-κB signaling axis in vivo." (PMID 40825934, 2025). "Based on the findings of this study, METTL3 could potentially serve as a novel therapeutic target for the management of HP-induced Gastritis." (PMID 40825934, 2025). "In the future, further validation and a more comprehensive understanding of the role of METTL3 in HP-induced Gastritis could be attained by increasing the utilization of databases and tools." (PMID 40825934, 2025). "Finally, we investigated whether HP exacerbates the inflammatory response in gastritis mice through the METTL3/CXCL1/NF-κB signaling axis." (PMID 40825934, 2025). "This study investigates the role of METTL3, an enzyme involved in m6A methylation, in modulating the CXCL1/NF-κB signaling pathway in H. pylori-induced gastritis." (PMID 40825934, 2025). "This study uncovers the role of METTL3 in regulating CXCL1 expression through m6A modification, thereby activating the NF-κB signaling pathway in the pathogenesis of HP-induced gastritis." (PMID 40825934, 2025). "The correlation between METTL3 and CXCL1 suggests a potential therapeutic target for HP-induced gastritis." (PMID 40825934, 2025). "This study confirms the roles of METTL3 and CXCL1 in HP-induced Gastritis while also elucidating their connection to the NF-κB signaling pathway." (PMID 40825934, 2025). "Taken together, METTL3 knockdown alleviated apoptosis and inflammation in the gastric mucosa of HPI gastritis mice." (PMID 40825934, 2025). "In conclusion, METTL3 upregulates CXCL1 expression through m6A modification, activating the NF-κB signaling pathway and exacerbating the inflammatory response in HPI-induced gastritis in mice." (PMID 40825934, 2025). "Recent studies suggest that METTL3 may play a role in regulating the m6A modification of CXCL1, which is involved in the inflammatory response of Gastritis and subsequently affects the NF-κB signaling pathway." (PMID 40825934, 2025). "However, it sheds new light on the specific mechanism of METTL3 in HP-infected Gastritis, which has not been reported before." (PMID 40825934, 2025).
graft versus host disease (1 paper, 2023). An immune system disorder that occurs after allogeneic hematopoietic stem cell transplant and is a reaction of donor immune cells against host tissues. "In vivo evaluation of METTL3 inhibition on CD4+ T-cell activation, effector T-cell differentiation, and SLE pathogenesis was achieved using a sheep red blood cell (SRBC)-immunized mouse model and a chronic graft versus host disease (cGVHD) mouse model." (PMID 37013484, 2023).
haemorrhagic fever (1 paper, 2023). "To assess whether the role of m6A and METTL3 is specific for the filovirus EBOV or a more common feature of haemorrhagic fever-causing NSVs, we also assessed the importance of METTL3 for the arenavirus JUNV and the orthonairovirus CCHFV." (PMID 37306620, 2023). "Again, similar results were obtained for JUNV and CCHFV, supporting the observation that the main function of METTL3 in the life cycles of haemorrhagic fever-causing NSVs is not due to inhibition of the IFN-β response." (PMID 37306620, 2023). "Taken together, we have shown that METTL3 methylates EBOV mRNAs, is recruited to EBOV inclusion bodies as the sites of viral RNA synthesis, and plays an important role in viral RNA synthesis of not only EBOV but also other haemorrhagic fever-causing NSVs (i.e. JUNV and CCHFV)." (PMID 37306620, 2023).
HCMV infection (1 paper, 2022). "The proportion of apoptotic cells during HCMV infection was significantly reduced after METTL3 or YTHDF3 knockdown." (PMID 35359726, 2022). "It was observed that HCMV infection significantly increased luciferase activity, whereas this effect was rescued by METTL3 knockdown in HAECs." (PMID 35359726, 2022). "First, we investigated whether METTL3 or METTL14 (two m6A methyltransferases upregulated by HCMV infection) regulate MCU expression." (PMID 35359726, 2022). "Mechanistically, HCMV infection could induce aberrantly elevated m6A modification, especially the increases of methyltransferases-“writers” (METTL3) and m6A binding proteins-“readers” (YTHDF3)." (PMID 35359726, 2022). "HCMV infection not only upregulated YTHDF3 expression but also promoted its binding to MCU mRNA, and this interaction was significantly decreased after METTL3 knockdown." (PMID 35359726, 2022). "It was observed that the mRNA levels of METTL3, METTL14, YTHDF1, YTHDF2, and YTHDF3 were significantly increased in HAECs following HCMV infection." (PMID 35359726, 2022). "In addition, knockdown of METTL3 in HCMV-infected HAECs similarly reduced the increase in protein expression of MCU induced by HCMV infection (mRNA expression was not affected)." (PMID 35359726, 2022). "However, silencing METTL3 but not METTL14 resulted in decreased MCU m6A methylation levels under HCMV infection conditions, suggesting that MCU mRNA may be subject to METTL3-dependent m6A methylation." (PMID 35359726, 2022).
HIV-1 infection (1 paper, 2025). The type species of lentivirus and the etiologic agent of acquired immunodeficiency syndrome (AIDS). "Overall, our results suggest that HIV-1 infection of CD4+ T cells causes an increase in the interaction between METTL3 and 14 that is associated with an increase in m6A levels." (PMID 41085277, 2025). "We observed that HIV-1 infection promotes the interaction between METTL3/METTL14." (PMID 41085277, 2025). "We found that HIV-1 infection enhances the METTL3/14 interaction in CD4+ T cells." (PMID 41085277, 2025). "Next, we tested whether the interaction between METTL3 and 14 could be changed by HIV-1 infection in Jurkat cells." (PMID 41085277, 2025). "Here, we demonstrate that HIV-1 infection of activated primary CD4+ T cells promotes the interaction between the m6A writer complex subunits methyltransferase-like 3 and 14 (METTL3/METTL14)." (PMID 41085277, 2025).
Hutchinson-Gilford progeria (1 paper, 2022). "The m6A modifications in Hutchinson-Gilford progeria (HGPS) and Werner syndrome (WS) increased with METTL3 overexpression and delayed disease progression." (PMID 35518355, 2022).
hyperuricemia (1 paper, 2025). An abnormally high level of uric acid. "Silencing METTL3 in mice can improve the decline of the ABCG2 mRNA level caused by hyperuricemia; consistent results have been observed in vitro." (PMID 40100069, 2025). "Hyperuricemia led to elevated m6A levels and METTL3 expression in mouse kidneys." (PMID 40100069, 2025).
Immunodeficiency (1 paper, 2024). Failure of the immune system to protect the body adequately from infection, due to the absence or insufficiency of some component process or substance. "The observed regulation in Vero cells may be attributed to the immunodeficiency of Vero cells, characterized by a lack of IFN-I production, which might in turn inhibit the transcriptional expression of METTL3." (PMID 39759074, 2024).
ischemia reperfusion injury (1 paper, 2022). Adverse functional, metabolic, or structural changes in ischemic tissues resulting from the restoration of blood flow to the tissue (reperfusion), including swelling; hemorrhage; necrosis; and damage from free radicals. "For example, ischemia-reperfusion injury (IRI) and hypoxia/reoxygenation (H/R) cardiomyocytes in mice have been shown to downregulate METTL3, whilst the overexpression of METTL3 has been shown to mitigate the IRI and H/R-induced cells' death." (PMID 36061306, 2022).
ischemic disease (1 paper, 2020). Lack of blood supply to an area of the body, resulting in impairment of tissue oxygenation. "In addition, transcription factor EB activates the transcription of ALKBH5 and downregulates the stability of METTL3 mRNA in hypoxia/reoxygenation-induced autophagy in ischemic diseases." (PMID 31931709, 2020).
joint diseases (1 paper, 2025). "In summary, while the current body of research sheds light on the potential roles of METTL3 in bone and joint diseases, significant gaps remain in our understanding of its mechanisms of action, particularly concerning DNA methylation." (PMID 40052548, 2025). "Moreover, the intricate relationship between METTL3 and DNA methylation in the context of bone and joint diseases warrants a deeper exploration." (PMID 40052548, 2025).
leiomyoma (1 paper, 2026). A well-circumscribed benign smooth muscle neoplasm characterized by the presence of spindle cells with cigar-shaped nuclei, interlacing fascicles, and a whorled pattern. "Here, we investigated the role of METTL3-associated signaling in mediating the anti-leiomyoma effects of quercetin." (PMID 42196565, 2026).
lichen planus (1 paper, 2025). A chronic, recurrent, pruritic inflammatory disorder of unknown etiology that affects the skin and mucus membranes. "Immunohistochemical results revealed that METTL3 was highly expressed in MF tissue samples compared with lichen planus." (PMID 40332203, 2025). "Our study shows that METTL3 expression is increased in mycosis fungoides compared with the inflammatory disease lichen planus, revealing that elevated METTL3 expression may act as an oncogenic driver in CTCL progression." (PMID 40332203, 2025).
memory impairment (1 paper, 2021). "Signifying the critical role of the appropriate m6A equilibrium in the hippocampal function in adult mice, reduced m6A deposition induced by METTL3 knockdown in the hippocampus of adult mice caused significant cognitive/memory impairment." (PMID 34593014, 2021).
metastatic colorectal cancer (1 paper, 2021). "Studies have shown that METTL3 is highly expressed in metastatic colorectal cancer and is related to poor prognosis." (PMID 34814861, 2021).
metastatic prostate carcinoma (1 paper, 2024). A carcinoma that arises from the prostate gland and has spread to other anatomic sites. "Next, it was found that METTL3 expression was decreased and FTO expression was increased in the metastatic prostate cancer samples." (PMID 38384328, 2024).
migraine (1 paper, 2025). "This mechanistic axis not only bridges RNA epitranscriptomics with neurovascular dysregulation but also positions METTL3 and miR-34a-5p as potential therapeutic targets for mitigating migraine-associated nociceptive sensitization." (PMID 41039196, 2025). "Dysregulation of METTL3-mediated m6A modification in neurons has been linked to aberrant synaptic plasticity, neuronal excitability, and neuroinflammation, all of which are closely related to migraine mechanisms." (PMID 41039196, 2025). "Moreover, other signaling cascades such as the PI3K/AKT, MAPK, or NF-κB pathways—previously linked to migraine and neuroinflammation—may also be regulated by METTL3 either directly or indirectly." (PMID 41039196, 2025). "Given the higher prevalence and severity of migraine in women, it is critical to explore the role of METTL3 in female models and assess potential sex-specific regulatory mechanisms." (PMID 41039196, 2025). "In line with this, our study provides new evidence linking METTL3 to migraine pathophysiology, highlighting its role in TGVS activation and pain sensitization." (PMID 41039196, 2025). "This study aims to investigate the role of METTL3 in migraine, focusing on its m6A-dependent regulatory mechanisms." (PMID 41039196, 2025). "Our study demonstrates that METTL3, a key m6A methyltransferase, is significantly upregulated in migraine and contributes to disease progression by promoting the maturation of miR-34a-5p and regulating the Wnt1/β-catenin pathway." (PMID 41039196, 2025). "Despite these findings, the precise role of METTL3 in migraine and its downstream molecular pathways remains largely unexplored." (PMID 41039196, 2025). "Future studies using METTL3 catalytic mutants, RNA immunoprecipitation followed by sequencing (RIP-seq), or transcriptome-wide m6A profiling (MeRIP-seq) will be essential to distinguish m6A-dependent from m6A-independent functions of METTL3 in migraine." (PMID 41039196, 2025). "METTL3 contributes to migraine pathogenesis through m6A-dependent upregulation of miR-34a-5p, which suppresses the Wnt1/β-catenin axis and promotes TGVS activation." (PMID 41039196, 2025). "Depletion of METTL3 inhibits the activation of the trigeminovascular system, thereby alleviating migraine symptoms." (PMID 41039196, 2025). "Further studies using in situ hybridization or single-cell RNA-seq would be valuable to dissect the relative contribution of METTL3 in neurons versus glial cells under migraine conditions." (PMID 41039196, 2025). "The elevated expression of METTL3 in TG of migraine rats aligns with the established role of TGVS hyperactivity in migraine." (PMID 41039196, 2025). "Building on our findings that METTL3 promotes miR-34a-5p maturation via m6A-dependent processing, we next examined whether the pro-migraine effects of METTL3 are functionally dependent on miR-34a-5p." (PMID 41039196, 2025). "METTL3 expression was significantly upregulated in the trigeminal ganglia of migraine rats." (PMID 41039196, 2025). "While our study highlights the METTL3/miR-34a-5p/Wnt1 signaling axis as a key contributor to TGVS activation in migraine, we acknowledge that METTL3 may exert additional effects through alternative mechanisms." (PMID 41039196, 2025). "However, whether METTL3 upregulates the expression of miR-34a-5p by mediating m6A methylation modification of pri-miR-34a, and subsequently influences the pathogenesis of migraine through targeting Wnt1, remains to be elucidated." (PMID 41039196, 2025). "Knockdown of METTL3 reduced trigeminovascular system (TGVS) activation and alleviated migraine symptoms." (PMID 41039196, 2025). "Overall, METTL3 knockdown attenuates TGVS activation and alleviated migraine symptoms." (PMID 41039196, 2025). "The cell-autonomous action of METTL3 in neurons, independent of microglia, supports a distinct mechanistic axis in migraine pathophysiology." (PMID 41039196, 2025).
myopia (1 paper, 2023). "Among these signaling pathways, Wnt signaling pathway was the most enriched one that was potentially affected by myopia and potentially regulated by METTL3." (PMID 37355654, 2023).
nephritis (1 paper, 2024). Inflammation of renal tissue. "For example, METTL3 increased the m6A modification of TAB3 and promoted the stability of TAB3 in an IGF2BP2-dependent mechanism, leading to the development of nephritis." (PMID 39337381, 2024).
non-Hodgkin lymphoma (1 paper, 2023). Distinct from Hodgkin lymphoma both morphologically and biologically, non-Hodgkin lymphoma (NHL) is characterized by the absence of Reed-Sternberg cells, can occur at any age, and usually presents as a localized or generalized lymphadenopathy associated with fever and weight loss. "In natural killer/T-cell lymphoma (NKTCL), a type of non-Hodgkin’s lymphoma, METTL3 was up-regulated when compared to its expression in normal NK cells." (PMID 37907575, 2023).
odontogenic cyst (1 paper, 2024). A cyst in the jaw that arises from tissues of tooth development. "Lastly, the results of this study lead to the proposition that METTL3 may be useful as a biomarker to predict the severity of odontogenic lesions, though the precise molecular mechanism of METTL3 in odontogenic cysts and tumours still needs to be elucidated." (PMID 39822792, 2024).
oncocytoma (1 paper, 2021). "Compared to normal renal tissue protein expression of all investigated methyltransferases was increased in oncocytoma (METTL3 P < .001, METTL4 P < 0,001, METTL14 P = .003, KIAA1429 P = .001, WTAP P = .001)." (PMID 35474700, 2021).
oral epithelial dysplasia (1 paper, 2023). "14, 15, 16, 17However, there are limited data on the role of METTL3 in oral precancerous lesions, especially in oral epithelial dysplasia (OED)." (PMID 35785826, 2023). "However, there is limited information about the roles of METTL3 in oral epithelial dysplasia (OED)." (PMID 35785826, 2023).
oral submucous fibrosis (1 paper, 2022). "In addition, it is also strongly advised to adopt a mouse model to study the involvement of arecoline-induced METTL3 in oral submucous fibrosis transformation." (PMID 36429032, 2022).
ovarian endometriosis (1 paper, 2023). A non-neoplastic disorder characterized by the growth of endometrial tissue in the ovaries. "First, patients with DIE, a particular type of EMs, shows hyper METTL3 expression compared to other ovarian endometriosis alone specimens." (PMID 37353804, 2023).
ovarian serous cystadenocarcinoma (1 paper, 2025). A malignant serous cystic epithelial neoplasm arising from the ovary. "METTL3 confers resistance to oxaliplatin by activating G6PD to enhance the pentose phosphate pathway and leads to cisplatin resistance in OSCC, BRCA, ovarian serous cystadenocarcinoma (OV), and LUAD, suggesting the possibility of METTL3 inhibitor combined with platinum chemotherapy drugs." (PMID 41194259, 2025).
postmenopausal osteoporosis (1 paper, 2018). Metabolic disorder associated with fractures of the femoral neck, vertebrae, and distal forearm. "Furthermore, Mettl3 gain-of-function prevents estrogen deficiency-induced postmenopausal osteoporosis, establishing the indispensability of Mettl3 in defining bone marrow MSC’s fate and thereby ensuring skeletal health." (PMID 30429466, 2018).
prostatic hyperplasia (1 paper, 2022). "For investigating the specific effects of METTL3 on BPH, the prostatic hyperplasia model was induced in rats by subcutaneous injection of testosterone as described, and METTL3 knockdown was achieved in rat models by injecting lentivirus containing sh-METTL3." (PMID 35985997, 2022).
psoriasis vulgaris (1 paper, 2022). Plaque psoriasis is the most common presentation of psoriasis. "Based on these results, we assume that METTL3-mediated m6A methylation is closely related to the development of psoriasis vulgaris and that with increasing PASI score, m6A methylation gradually decreases." (PMID 36293529, 2022). "Our study demonstrated that METTL3-mediated m6A methylation participates in processes that are critical for the development of psoriasis vulgaris." (PMID 36293529, 2022). "Our results indicated the critical role of METTL3-mediated m6A methylation in the pathogenesis of psoriasis vulgaris." (PMID 36293529, 2022). "Our results indicate a critical role of METTL3- mediated m6A methylation in the pathogenesis of psoriasis vulgaris." (PMID 36293529, 2022). "In future work, the specific molecular mechanism by which METTL3-mediated RNA m6A methylation regulates the occurrence and development of psoriasis vulgaris should be further studied." (PMID 36293529, 2022).